IFT70B (intraflagellar transport 70B)
Description:
Required for polyglutamylation of axonemal tubulin. Plays a role in anterograde intraflagellar transport (IFT), the process by which cilia precursors are transported from the base of the cilium to the site of their incorporation at the tip.
Synonyms: TTC30B; FLJ30990; fleer; IFT70
Tractability: PROTAC: ubiquitination databases record sites on it.
Gene: Protein-coding gene on chromosome 2 (177,548,998 to 177,552,796, reverse strand). Ensembl gene ENSG00000196659.
Subcellular location: Cell projection, cilium
Subcellular location (Human Protein Atlas): Basal body; Centrosome; Primary cilium; Nucleoplasm; Primary cilium tip
Pathways (Reactome):
Organelle biogenesis and maintenance: Intraflagellar transport
Gene Ontology:
Molecular function: protein binding; intraciliary transport particle B binding
Biological process: cilium assembly; intraciliary anterograde transport; intraciliary transport
Cellular component: intraciliary transport particle A; intraciliary transport particle B; axonemal microtubule; ciliary tip; cilium; intraciliary transport particle
Genetic constraint (gnomAD): Loss-of-function variants: 32 observed, 45.44 expected, observed/expected ratio (o/e) 0.7, 90% interval 0.53 to 0.95. The upper end of that interval is the gene's LOEUF score, 0.95, which puts it in group 4 of 6, group 1 being the genes least tolerant of losing a copy. Missense variants: 699 observed, 777.15 expected, observed/expected ratio (o/e) 0.9, 90% interval 0.84 to 0.96. Synonymous variants: 304 observed, 311.06 expected, observed/expected ratio (o/e) 0.98, 90% interval 0.89 to 1.08.
Homologues: Orthologues: chimpanzee IFT70B (99% identical), macaque IFT70B (97% identical), mouse Ift70b (92% identical), dog TTC30A (92% identical), mouse Ift70a2 (92% identical), mouse Ift70a1 (90% identical), tropical clawed frog ift70a (80% identical), zebrafish ift70 (76% identical), rat Ift70a2 (73% identical), Caenorhabditis elegans dyf-1 (48% identical), Drosophila melanogaster Ttc30 (46% identical). Paralogues in human: IFT70A (95% identical).
Diseases named in the same sentence as IFT70B in open-access papers:
IFT70B is named in the same sentence as 1 disease in open-access papers, as found by Europe PMC text mining. Sharing a sentence is not in itself a finding about the gene and the disease.
IFT70B shares sentences with these, for which no sentence is quoted: ciliopathy (1 paper).